PLN (phospholamban)
Diseases named in the same sentence as PLN in open-access papers (continued):
Sharing a sentence is not in itself a finding about the gene and the disease.
dilated cardiomyopathy (continued). "Recently, a mutation of PLN in which one of the N-terminal di-arginine residues at positions 13 and 14 was deleted led to a severe, early onset dilated cardiomyopathy." (PMID 20634894, 2010). "A mutation of PLN in which one of the di-arginine residues at positions 13 and 14 was deleted led to a severe, early onset dilated cardiomyopathy." (PMID 20634894, 2010). "Phospholamban (PLN) plays a prime role in cardiac contractility and relaxation and mutations in the gene encoding PLN have been associated with dilated cardiomyopathy." (PMID 19638213, 2009). "Case Presentation: A 71-year-old patient with a history of dilated cardiomyopathy caused by a phospholamban (PLN) gain-of-function mutation, with a primary prevention ICD and an LVAD, presented with multiple ICD shocks which she experienced as painful and traumatic." (PMID 42029465, 2026). "The phospholamban (PLN) R14del genetic variant causes dilated cardiomyopathy." (PMID 40791987, 2025). "The PLN R9C mutation causes early-onset dilated cardiomyopathy (DCM) and premature death, yet the mechanisms underlying its pathogenic remodeling remain unclear." (PMID 41309526, 2025). "The PLN-R14del genetic variant is associated with dilated cardiomyopathy in patients." (PMID 40791987, 2025). "Null mutations in the PLN gene have been associated with lethal dilated cardiomyopathy in humans." (PMID 39273332, 2024). "These patients develop an aggressive dilated cardiomyopathy and genetically engineered mice recapitulating this myopathy suffer premature death, highlighting a pathophysiologic consequence associated with the disruption of the 14–3-3/PLN interaction." (PMID 34820713, 2022). "The “superinhibition hypothesis” suggested that agents opposing PLN-SERCA2a interaction might target the very mechanism of the dilated cardiomyopathy associated with the mutation." (PMID 34948294, 2021). "Interestingly, one patient with an R14del mutation in PLN developed late-onset mild dilated cardiomyopathy, but was initially evaluated in a muscle dystrophy clinic for a 25-year history of slowly progressive muscle weakness." (PMID 26035394, 2015). "Thus, the present findings should not be generalized; they only indicate that a dysfunction other that SERCA2a superinhibition may underlie the dilated cardiomyopathy associated with the PLN p.Arg14del mutation." (PMID 34948294, 2021). "A study identified the phospholamban (PLN) p.Leu39* variant in 4.8% of HCM patients and 3.2% of dilated cardiomyopathy (DCM) patients." (PMID 39507141, 2024). "In the last decade, several PLN mutations have been found to associate with arrhythmogenic cardiomyopathy (ACM) and dilated cardiomyopathy (DCM)." (PMID 34948294, 2021). "Mice harboring the PLN R14del pathogenic variant recapitulate the human dilated cardiomyopathy (DCM) phenotype; subcutaneous administration of PLN-ASO prevents PLN protein aggregation, cardiac dysfunction, and leads to a 3-fold increase in survival rate." (PMID 34462437, 2021). "It has been found that ILK, a mechanoreceptor protein, regulates SERCA-2a and PLN to improve the mechanical forces conduction of damaged cardiomyocyte in patients with dilated cardiomyopathy, and eventually ameliorating the myocardial systolic function." (PMID 29379038, 2018). "There is evidence that dilated cardiomyopathy in humans can result from chronic inhibition of SERCA2a by the prevention of phosphorylation of phospholamban by PKA." (PMID 24945867, 2014). "Hence the possible involvement of the R9C-PLN mutation in dilated cardiomyopathy might be explained, at least in part, by a modulation of the open probability of the PLN generated channel conductance; this would be a modulatory factor beyond the altered interaction of R9C with SERCA." (PMID 23308118, 2013).
dilated cardiomyopathy (continued). "While removing PLN can help with HCM, having one less copy of the PLN gene (heterozygous loss-of-function variants) in humans can lead to a different heart condition called dilated cardiomyopathy (DCM), making this approach less feasible for human treatment." (PMID 38540296, 2024). "However, the availability of a Ser10 specific PLN antibody revealed possible roles for this site in dilated cardiomyopathy and heart failure." (PMID 30742812, 2019). "Interestingly, in the MLP knockout mouse with dilated cardiomyopathy (enhanced basal SERCA activity) increased PLN phosphorylation is believed to limit FFR." (PMID 19125184, 2009). "For example, mutations in JUP, DSP, PKP2, DSG2, DSC2, CTNNA3, CDH2, or PLN (all of them more abundant in LV) predominantly lead to arrhythmogenic right ventricular cardiomyopathy, and mutations in MYH7, HSPB7, NEXN and MYPN (also all more abundant in LV) lead to dilated cardiomyopathy." (PMID 32291283, 2020). "For example, dilated cardiomyopathy (DCM), which is defined by systolic dysfunction and dilation of one or both ventricles, can be caused in humans by mutations in the genes encoding cardiac phospholamban (PLN), delta-sarcoglycan (SGCD), and RNA-binding protein 20 (RBM20)." (PMID 31490923, 2019). "Tamoxifen administration to mice expressing MerCreMer protein is known to induce severe, transient dilated cardiomyopathy that is accompanied by transient reduction in SERCA2 and phospholamban mRNA." (PMID 27313537, 2016). "One of such a non-desmosomal variant is in the phospholamban gene (PLN, p.Arg14del), which can cause next to ACM, also a dilated cardiomyopathy (DCM) phenotype in patients." (PMID 35008484, 2021). "Phospholamban is a Ca2+-ATPase, which triggered the hypothesis that Ca2+ homeostasis might play an important role in the pathogenesis of arrhythmogenic phenotype in p.Arg14del carriers with ACM or dilated cardiomyopathy (DCM)." (PMID 38892455, 2024).
cardiac hypertrophy (24 papers, 2009 to 2026). "The patient-specific CMs displayed Ca2+ handling abnormalities, electrical instability, abnormal cytoplasmic distribution of PLN protein and an increased expression of molecular markers associated with cardiac hypertrophy." (PMID 25923014, 2015). "The precise cardiac pathology of the different PLN mutations varies but most patients present with cardiac dilatation, hypertrophy, decreased ejection fraction and ventricular arrhythmias." (PMID 25923014, 2015). "We find that the PLN R14del mutation induces Ca2+ handling abnormalities, electrical instability, abnormal cytoplasmic distribution of PLN protein and increases expression of molecular markers of cardiac hypertrophy in iPSC-CMs." (PMID 25923014, 2015). "As expected, each of the phosphorylation levels of mTOR, ERK, TnI, PKD, HDAC5 and PLN was increased in PE-stimulated cardiomyocytes, supporting the use of PE stimulation as a suitable in vitro model of cardiac hypertrophy." (PMID 41596248, 2026). "LCA alleviates high-glucose-induced cardiac hypertrophy via enhancing sarcoplasmic/endoplasmic reticulum Ca2+ ATPase 2a (SERCA2a) and phosphorylated phospholamban (PLN) expression in H9C2 cells, thereby activating TGR5." (PMID 36014536, 2022). "Overexpression of PLN-R14del resulted in superinhibition of SERCA, associated with cardiac hypertrophy, myocardial fibrosis, and premature death between 2 and 16 weeks of age." (PMID 32555305, 2020). "To unravel the effect of MI14 on the signaling pathways involved in the development of cardiac hypertrophy, we examined phosphorylation levels of the hypertrophy-associated kinases mTOR, ERK, PKD, the MEF2 adaptor HDAC5 and the Ca2+ dynamics regulator phospholamban (PLN)." (PMID 41596248, 2026). "Furthermore, improvements to SERCA activity and its Ca2+ sensitivity via alterations in the SERCA2:PLN ratio can play a role in the regulation of cardiac hypertrophy and remodeling." (PMID 40170524, 2025). "In agreement with previous findings, the majority of our PLN p.Leu39* patients demonstrated cardiac hypertrophy, supporting the hypothesis that p.Leu39* is an HCM-predisposing variant." (PMID 38392255, 2024). "Recent studies found that irregular Ca2+ handling, abnormal cytoplasmic PLN protein distribution, and increased cardiac hypertrophy marker expression could be exhibited in the iCMs carrying a deleterious PLN R14del mutation." (PMID 39465141, 2024). "Moreover, the PLN-SERCA2a pathway plays an important role in the pathogenesis of cardiac hypertrophy." (PMID 35185583, 2022). "In addition, we observed an increase in the markers of cardiac hypertrophy and an abnormal cytoplasmic PLN protein distribution in CMs." (PMID 25923014, 2015). "cardiac hypertrophy, cancer, cell death and survival with upregulation of proteins such as MYH7, MYL2, APOA1 and phospholamban (Table of Top enriched networks from core analysis of both H9c2 and GK overexpressed proteins S1 Table)." (PMID 34166385, 2021). "Additionally, our study demonstrated that treatment with Tirzepatide increased the expression and activity of SERCA2 and phosphorylated PLN and decreased the expression of PKA and CAMKII, essential modulators of calcium signaling and cardiac hypertrophy." (PMID 38555463, 2024). "PLN deletion significantly reduced atrial hypertrophy, but not ventricular hypertrophy." (PMID 27992596, 2016).
Ventricular arrhythmia (22 papers, 2013 to 2025). "For example, mutations in LMNA and PLN have been associated with a higher prevalence of ventricular arrhythmias and sudden cardiac death than those in sarcomeric genes." (PMID 40080479, 2025). "Sedentary Obscn-R4344Q mice developed spontaneous ventricular arrhythmia by 12 months associated with increased Ca2+ cycling kinetics, linked to enhanced binding of phospholamban (PLN) to mutant Ig58-R4344Q." (PMID 39804820, 2025). "It is well known that the PLN p.Arg14del founder variant (NM_002667.5) is characterized by life-threatening ventricular arrhythmias and sudden cardiac death, highlighting a potentially primary arrhythmogenic nature of this variant." (PMID 38392255, 2024). "Of note, NICMP is a heterogeneous condition with a variety of causes, and the risk of life-threatening ventricular arrhythmias is higher in some conditions (e.g. sarcoidosis, phospholamban mutation)." (PMID 36066840, 2023). "The natural mutation R9H has recently been shown to cause ventricular arrhythmias in dogs, indicating that PLN mutations other than R14del can be arrhythmogenic." (PMID 34320358, 2021). "In one study, the authors evaluated possible risk factors for malignant ventricular arrhythmias in a large cohort of individuals carrying the PLN R14del mutation." (PMID 30547415, 2019). "A Canadian cohort of patients with the phospholamban R14del mutation had a malignant course with frequent biventricular cardiomyopathy and ventricular arrhythmias." (PMID 30806910, 2019). "Mutations in genes such as LMNA, PLN, RBM20, and FLNC are associated with an increased risk of ventricular arrhythmias (VA) and SCD." (PMID 40711538, 2025). "Of the patients with diagnostic variants, 15.8% (81/514) had a variant in genes that have been associated with increased risk of ventricular arrhythmias (LMNA, RBM20, FLNC, and PLN)." (PMID 37795486, 2023). "Furthermore, knocking out phospholamban in heterozygous R4496C mice strongly increases Ca2+ sparks but reduces cell-wide Ca2+ waves preventing ventricular arrhythmia in these mice." (PMID 34831263, 2021). "iii) Daily exercise increased the ventricular arrhythmia threshold by altering calcium regulatory proteins such as a decrease in the protein expression of the Na+/Ca2+ exchanger and as normalization of the protein expression of phospholamban in the hypertensive rats." (PMID 23825553, 2013). "The detection of the PLN p.Leu39* variant facilitated targeted interventions and family screening, revealing a distinct clinical profile with higher incidences of non-sustained ventricular arrhythmias and elevated N-terminal pro-B-type natriuretic peptide levels." (PMID 39507141, 2024). "Additionally, DCM patients with a PLN mutation present with ventricular arrhythmias and experience appropriate implantable cardioverter defibrillator (ICD) therapy more often than DCM patients without a PLN mutation." (PMID 30547415, 2019).
Arrhythmia (21 papers, 2007 to 2025). Any cardiac rhythm other than the normal sinus rhythm. "As proof of concept, we screened 20 AF-associated genes and identified phospholamban loss of function as a top conserved hit that shortens action potential duration and increases the incidence of arrhythmia phenotypes upon stress." (PMID 37293707, 2023). "Collectively, our findings suggest that PLN loss of function predisposes cells to arrhythmia in a tissue environment with reduced electrical coupling and elevated β-adrenergic activity." (PMID 37293707, 2023). "This, in turn, promotes SR Ca2+ leak and cardiac arrhythmias, as evidenced in patients carrying the R14del-PLN mutation." (PMID 36768995, 2023). "In agreement with our results, many proteins of the PLN regulatory network are in fact associated with cardiac arrhythmias by both experimental and clinical data." (PMID 34320358, 2021). "Cardiac arrhythmias such as ventricular tachycardias and fibrillation are also a hallmark of the pathogenic PLN mutation R14del." (PMID 34320358, 2021). "Multiple mutations in the PLN gene have been discovered in the past two decades, most of which cause severe forms of cardiomyopathy and lead to cardiac arrhythmias or heart failure." (PMID 34320358, 2021). "Phospholamban R14del mutation carriers and family members were identified from inherited arrhythmia clinics at 13 sites across Canada." (PMID 30806910, 2019). "Overall, gene editing and pharmacological approaches have rendered promising findings on therapeutic strategies in preventing Ca2+ dysregulation, improving contractility and reducing arrhythmia susceptibility in order to alleviate these key pathological features of PLN-R14del pathophysiology." (PMID 37144056, 2023). "Thus, collectively, our results indicate that reduced PLN function predisposes ACMs to arrhythmia upon sensitization by fibroblasts and acute β-adrenergic stimulation." (PMID 37293707, 2023). "Since R14del-PLN is associated with arrhythmogenic RV cardiomyopathy in humans, we investigated whether there were any cardiac arrhythmias in vivo." (PMID 34204946, 2021). "Preliminary analyses suggest that the PLN mutation R14del could impair noise filtering, offering a new perspective on how this mutation causes cardiac arrhythmias." (PMID 34320358, 2021). "Since cardiac arrhythmias are a major issue for patients with the PLN mutation R14del, we wanted to know whether noise filtering is impaired if we implement the known molecular effects of this mutation into our model." (PMID 34320358, 2021). "Homozygous PLN-R14del mice exhibited an accelerated phenotype including cardiac dilatation, contractile dysfunction, decreased ECG potentials, high susceptibility to ex vivo induced arrhythmias, myocardial fibrosis, PLN protein aggregation, and early mortality." (PMID 32555305, 2020). "Furthermore, the hearts of PLN-R14Δ/+ mice were more susceptible to develop induced arrhythmias ex vivo, even at an early age when other cardiac abnormalities were absent." (PMID 32555305, 2020). "However, our current work suggests that the R14del-PLN mutation may increase the propensity to arrhythmia even at an early age in mice, similar to the increased risk of malignant VT in young patients." (PMID 34204946, 2021). "Other genes include lamin A/C (LMNA), linked to a high risk of arrhythmias and sudden cardiac death, filamin C (FLNC), phospholamban (PLN), β-myosin heavy chain (MYH7), cardiac troponin T (TNT2) and desmin (DES)." (PMID 41464586, 2025). "Treated mice also presented reduced mutant PLN transcript levels and PLN protein expression, partially improved cardiac function, and reduced arrhythmia vulnerability." (PMID 38785523, 2024). "Collectively, our results indicate that PLN KD-dependent arrhythmia phenotypes are, at least in part, mediated by NCX and LTCC activity." (PMID 37293707, 2023).
Arrhythmia (continued). "In this study, we identified PLN loss of function as the top hit, among the 20 AF-associated genes tested, causing both APD shortening and arrhythmia phenotypes (i.e. beat-to-beat interval irregularities, DADs) when combined with environmental perturbagens." (PMID 37293707, 2023). "A R9H mutation in the phospholamban (PLN) gene was recently identified in a pedigree of Welsh springer spaniels who had a high incidence of left ventricular dilation, arrhythmia, and early sudden cardiac death." (PMID 35804579, 2022). "Recently, a mouse model with insertion of the R14del mutation in the endogenous PLN locus was generated, and while homozygous mice died young with dilated cardiomyopathy (DCM), heterozygous mice showed a propensity to arrhythmia only at an old age (18 months)." (PMID 34204946, 2021). "Taken together, these data demonstrated impairment in Ca2+ handling properties of iPSC-derived CMs characterized by arrhythmias, suggesting a critical role of abnormal Ca2+ handling in the pathogenesis of DCM induced by the R14del mutation of PLN." (PMID 25923014, 2015). "Phospholamban-null mice in a 129 background respond to high doses of ouabain with a similar arrhythmia (9/10) and death (8/10) in the same manner as C57BL/6 WT mice (8/8, 6/8) and 129 WT mice (9/10,8/10)." (PMID 17940615, 2007). "For example, although PLN-Leu39Ter heterozygosity has been reported to lead to HCM, in the presence of three additional genetic variants in DCM/arrhythmia associated genes, a PLN-Leu39Ter heterozygote patient presented with DCM and sustained ventricular tachycardia." (PMID 40556736, 2025). "These simulations suggest that LTCCs and NCX modify PLN activity and contribute to regulate rhythm in atrial myocytes, and thus they might represent a class of second hits contributing to promote PLN KD-induced arrythmias." (PMID 37293707, 2023). "Additionally, the overstimulation of RAAS and the prolonged activation of PKC-dependent signaling cascades could facilitate cardiac arrhythmia via CaMKII-mediated phosphorylation of calcium-handling proteins, notably RyR2 and phospholamban (PLN)." (PMID 34445698, 2021). "Thus, to test whether inhibition of LTCC activity might reduce PLN-induced arrhythmia phenotypes, we treated ACMs with a Ca2+ channel blocker, verapamil, and quantified the percentage of arrhythmic cells in response to PLN KD+co-culture with fibroblasts+isoproterenol treatment." (PMID 37293707, 2023). "In summary, our findings in humanized R14del-PLN mice indicate decreases in the maximal force with parallel increases in the Ca2+ affinity of myofilaments which may contribute to overall impaired Ca2+ cycling and increased propensity to arrhythmias in mutant mice." (PMID 36768995, 2023). "A preliminary analysis of the arrhythmogenic PLN mutation R14del suggests that this mutation could impair noise filtering, indicating that molecular noise filtering in the β-adrenergic signaling network could be important to prevent cardiac arrhythmias." (PMID 34320358, 2021). "The action of psilocin can be compared with that of serotonin: 5-HT increased the phosphorylation state of phospholamban in the atrium of 5-HT4-TG and in isolated, perfused hearts of 5-HT4-TG, but not those of WT, and this led to arrhythmias." (PMID 40732298, 2025).